CD4 (CD4 molecule)
Diseases named in the same sentence as CD4 in open-access papers (continued):
Sharing a sentence is not in itself a finding about the gene and the disease.
leishmaniasis (continued). "In addition, it was observed that there was an increase in the number of CD4+ T cells producing IL-10, which is also positive, since a regulatory profile is also important during leishmaniasis, as an uncontrolled Th1 response is also part of the pathogenesis of this disease." (PMID 40006676, 2025). "In addition, assessing the induction of CD4+ TRM cells could be used as a biomarker of immune protection against leishmaniasis in evaluating the efficacy of candidate vaccines." (PMID 38469319, 2024). "Moreover, the literature contains no reports that directly link CD4+ T-cells specific to Leishmania antigens with clinical manifestations of leishmaniasis in association with IRIS." (PMID 25645330, 2015). "For the first time in human leishmaniasis, in individuals with a history of CL, a mixture of Leishmania-responsive CD4+ TEM cells capable of producing IFN-γ and Leishmania-responsive CD4+ TCM cells capable of producing IL-2 was detected." (PMID 38469319, 2024). "Although the CD69 marker has been assessed as an activation marker in CD4+ and CD8+ T-cell compartments in blood and skin lesion of human leishmaniasis patients, insufficient data are available regarding the involvement of TRM cells in human leishmaniasis." (PMID 38469319, 2024). "Given the intracellular nature of Leishmania parasites, helper type-1 CD4+ (Th1) and cytotoxic CD8+ T-cells (CTLs) are key regulators in controlling leishmaniasis." (PMID 37323936, 2023). "Models for the development of CD4 and CD8 T-cell quality in memory and protection to leishmaniasis have been described previously." (PMID 34777391, 2021). "Our studies show that IL-4 produced during the early timepoints following infection plays a central role in programming CD4+ and CD8+ T cell responses that promote leishmaniasis in BALB/c mice." (PMID 32948646, 2020). "CD4+ and CD8+ T cells play vital protective roles in fighting leishmaniasis and protecting the host from damage." (PMID 32176727, 2020). "Resisting leishmaniasis is concerned with a Th1 prevailing reaction as well as interleukin-2 (IL-2) and IFN- γ generation by the particular T lymphocyte+CD4 population of the antigen, through mediating protective cellular immune responses." (PMID 31579449, 2019). "Conversely in Leishmaniasis, CD4+CD25+ Treg cells are reported to suppress the ability of CD4+CD25- effector T cells to eliminate the parasites L. major at the site of infection in C57BL/6 mice." (PMID 31393896, 2019). "Our results suggest that CD4+ and CD8+ T cells are more related to leishmaniasis protection in EO than B cells." (PMID 28208616, 2017). "More recently, a balance between the proportion of CD4+ and CD8+ cells has been reported to be important for leishmaniasis healing." (PMID 28416006, 2017). "T CD4+ and T CD8+ cells are more related to leishmaniasis protection in experimental outcomes than B cell predicted epitopes." (PMID 28208616, 2017). "Multifunctional T CD4+ cells producing IFN-γ, TNF-α and IL-2 were correlated with protection against murine experimental leishmaniasis and were recently detected in individuals healed of L. braziliensis infection." (PMID 28416006, 2017). "Our results confirm that a balance between the proportion of CD4+ and CD8+T cells is important for leishmaniasis healing." (PMID 26485398, 2015). "The control of Leishmania infection is dependent on cellular immune mechanisms, and evidence has shown that CD4 and CD8 T lymphocytes play different roles in the outcome of leishmaniasis." (PMID 25325049, 2014). "This is of particular relevance for L. major infection, since CD4+CD25+ Tregs prevent a sterile cure, and therefore, there is potential for reactivation of leishmaniasis." (PMID 24205367, 2013). "The few studies aimed to understand the dynamics of memory CD4+ T cell populations in mouse model of leishmaniasis showed that early following infection of C57BL/6 mouse, both central and effector memory CD4+ T cells are generated." (PMID 24206576, 2013).
leishmaniasis (continued). "In experimental models of leishmaniasis, CD8+ T cells, in cooperation with CD4+ T cells, appear to be involved in the induction of host immunity against both primary infection and reinfection of Leishmania parasite." (PMID 20967288, 2010). "Therefore, we investigated whether leishmaniasis could impact T lymphocytes activation in HIV-1 co-infected patients through the analysis of CD4+ T absolute counts and of the proportion of CD8+ T cells expressing CD38 in Leishmania/HIV co-infected patients recovered after anti-leishmanial therapy." (PMID 21171992, 2010). "Overall, this review highlights the importance of memory T cells, particularly skin-resident CD4+ TRM cells, as promising targets for developing effective vaccines against leishmaniasis and as biomarkers of immune protection to assess the efficacy of candidate vaccines against human leishmaniasis." (PMID 38469319, 2024). "The low CD4 count suggests that a systemic TH2 response may have predominated, making it difficult to control the leishmaniasis." (PMID 39186781, 2024). "The antibody isotype profile is correlated with the protective and non-protective against leishmaniasis, Th1 and Th2 CD4+ T cell differentiation, respectively." (PMID 33428610, 2021). "The data presented in this study represents a step forward in the identification of both CD4+ and CD8+ specific T cell epitopes that could be exploited for the design of a polytope vaccine against leishmaniasis." (PMID 32176691, 2020). "Interestingly, this T-cell dysfunction was observed months after the initiation of the Leishmaniasis treatment, despite the increase of costimulatory molecules after SLA stimulation, and it resulted in low IFN-γ in CD8+ and CD4+ and granzyme B on CD8+." (PMID 29867989, 2018). "The significant recognition of LACK by the T receptors of the present cured and asymptomatic subjects, plus the ability of this protein to induce IFN-γ, TNF-α, and granzyme B (CD4+ and CD8+ T cell responses), indicates this antigen to be of potential use in vaccines against human leishmaniasis." (PMID 29740446, 2018). "Since Leishmania antigen-specific CD4+ and CD8+ T cells are essential for immunity against leishmaniasis, the protective effect of these populations detected in the present study was assessed by challenging vaccinated mice with a highly virulent strain of L. infantum promastigotes." (PMID 28114333, 2017). "Importantly, we found that TRM cells provided protection independently of circulating CD4+ T cells, emphasizing the importance of generating TRM cells for optimal immunity to leishmaniasis." (PMID 28419151, 2017). "In this investigation, we identified the NH36 domains and epitopes that induce CD4+ and CD8+ T cell responses, which could be used to potentiate a human universal T-epitope vaccine against leishmaniasis." (PMID 28321221, 2017). "As is the case for CD4+ T cells, CD8+ T cells are mostly host protective but may also drive pathology, depending on the form of leishmaniasis and disease staging." (PMID 28498840, 2017). "Inborn differences within Leishmania species, the pertinent disease and a good understanding of the immunopathological mechanisms displayed by CD4+ and CD8+ T cells must be kept in mind when planning new therapeutic and vaccine strategies in human leishmaniasis." (PMID 27092123, 2016). "Both CD4 and CD8 T cells are source of IFN-γ and are essential for resolution of leishmaniasis." (PMID 25568967, 2015). "In a non-healing mouse model of Leishmaniasis, high frequency of IL-10 producing regulatory T cells (CD4+CD25+FoxP3+) is observed at local site." (PMID 25032977, 2014). "The immune parameters induced against LACK and triggered by the combined vaccination DNA/MVA protocol, like polyfunctionality of CD4+ and CD8+ T cells with an effector phenotype, could be relevant in protection against leishmaniasis." (PMID 22715418, 2012).
leishmaniasis (continued). "The co-production of IL-10 by IFNγ-producing CD4+ T cells is not novel for leishmaniasis, however, and is now a recognized feature of Th1 cell differentiation." (PMID 22911108, 2012). "Both types of co-infected patients and the HIV-1 infected patients without leishmaniasis had much lower levels of CD4+ T counts when compared to healthy donors (p < 0.001)." (PMID 21171992, 2010). "Both AVL and ATL tend to emerge as opportunistic diseases in HIV infected patients without leishmaniasis especially in those presenting with CD4+ T cell levels below 350 cells/mm3." (PMID 21171992, 2010). "The findings presented here provide a novel mechanism that explains the incapacity of CD4+ T cells to mount an efficient response in the nonhealing form of leishmaniasis." (PMID 19597544, 2009). "Murine Leishmaniasis models have been pivotal in demonstrating Tregs at the site of (parasitic) infection: antigen-specific CD4+CD25+ Tregs were present at the site of chronic Leishmania major infection and retention at the infection site was dependent on expression of CD103 by CD4+CD25+ Tregs." (PMID 26029205, 2015). "In other words, at providing immunity to rechallenge in leishmaniasis central memory CD4+ T cells that could be maintained without persistent parasites were less effective." (PMID 24744757, 2014). "Most of the studies performed on human immune response against leishmaniasis is carried out on crude PBMCs without purifying CD4+ T cell and CD8+ population and there is no report to show a clear-cut CD4+ Th1/Th2 response." (PMID 20967288, 2010).
periodontitis (116 papers, 2012 to 2026). An acute or chronic inflammatory process that affects the tissues that surround and support the teeth. "In summary, our findings demonstrate that RATEVs suppress CD4+ T‐cell‐mediated inflammatory and osteolytic responses and ameliorate alveolar bone loss in experimental periodontitis, likely through mechanisms involving the CD73/ADO signalling pathway." (PMID 40620009, 2025). "The estimated OR for CD39 + CD4 + T cell in relation to the risk of periodontitis was 0.963 (95% CI = 0.939–0.987, P = 2.411 × 10−3, FDR = 0.112)." (PMID 39686447, 2024). "The IVW method estimated an OR of 0.964 (95% CI = 0.940–0.987, P = 2.740 × 10−3, FDR = 0.112) for CD39 + secreting CD4 regulatory T cell in relation to the risk of periodontitis." (PMID 39686447, 2024). "This case reported an early-onset periodontitis accompanied by vitamin D deficiency in adolescence, and ulteriorly elaborated on inversion of CD4+/CD8+ ratio as well as the decreased bone density brought by vitamin D deficiency." (PMID 37773856, 2023). "Tregs are a subset of CD4+ T cells that exhibit an opposite function to Th17 lymphocytes by being able to protect against inflammation and alveolar bone loss during periodontitis." (PMID 35269683, 2022). "Although periodontitis is caused by pathogenic bacteria, its progression and prognosis are highly influenced by CD4+T cell-mediated host immune response." (PMID 33981487, 2021). "Since CD4+ T cells participate in periodontitis-induced bone loss, we next investigated the impact of bindarit on the recruitment of CD4+ T cells to the inflamed periodontium." (PMID 32678310, 2021). "More importantly, ART-naïve, patients with CD4 < 200 cells presented with higher risk of having periodontitis compared to those with higher CD4-values, with a threefold difference (OR 3.21)." (PMID 33308188, 2020). "The associations between the occurrence of periodontitis with a low CD4 and age were seen to be higher in naïve patients." (PMID 33308188, 2020). "It’s worth noting that ART-naïve population with CD4 cells less than 200 had three times higher risk of having periodontitis than the ART group." (PMID 33308188, 2020). "The absolute number of CD4 cells pose an immunological risk factor for infections, such as periodontitis, and it was calculated that this risk factor is twice as high as compared to smoking." (PMID 30186883, 2018). "Since CD4+ T cells have been shown to be essential for the periodontitis-induced bone loss, we investigated which subsets of CD4+ T cells were increased during oral infection." (PMID 29453398, 2018). "In HIV-seropositive patients, the risk of progression from gingivitis to periodontitis is known to increase in proportion with immune function deterioration and decreased number of CD4 counts." (PMID 25614845, 2014). "Although this study provides robust evidence supporting the role of CD73/ADO signalling in mediating the immunosuppressive and anti‐osteolytic effects of RATEVs on CD4+ T lymphocytes and alveolar bone loss in experimental periodontitis, several key questions remain unanswered." (PMID 40620009, 2025). "Additionally, IFN-γ increases RANKL in CD4+ T cells, contributing to bone loss in diseases like periodontitis." (PMID 39768138, 2024). "The decrease of CD4 + /CD8 + ratio in gingival tissue reflects periodontitis and may be associated with severe adverse outcomes in people with ACS." (PMID 38451305, 2024). "Similarly, For CD4 on effector memory CD4 + T cell in relation to the risk of periodontitis was 1.169 (95% CI = 1.056–1.295, P = 2.735 × 10−3, FDR = 0.112)." (PMID 39686447, 2024). "Consequently, the predictive value of CD4 + /CD8 + ratio in gingival tissue during the follow-up of patients with periodontitis as an independent risk factor for ACS + P needs future prospective studies involving more patients." (PMID 38451305, 2024).
periodontitis (continued). "In addition, correlation analysis showed that CD53, CYBB, and PLEK were significantly positively linked with activated CD4+T cells in the immune microenvironment of peri‐implantitis, making them effective biomarkers to differentiate it from periodontitis." (PMID 38780047, 2024). "Finally, we discuss the existing literature that allows us to suggest the potential pathogenic role of senescent CD4+CD28− T lymphocytes in periodontitis." (PMID 35269683, 2022). "Therefore, it could be suggested that senescent CD4+CD28− T lymphocytes may play an important role in the pathogenesis of alveolar bone loss characteristic of periodontitis." (PMID 35269683, 2022). "Studies revealed that by causing peripheral CD4+ T helper cells to give rise to excessive amounts of pro-inflammatory cytokines, including IL-1β and IL-6, P. gingivalis could help in better understanding severe periodontitis." (PMID 36289921, 2022). "Role of the SASP produced by senescent CD4+ T lymphocytes in periodontitis-associated alveolar bone resorption: To elucidate the potential role of senescent CD4+ T lymphocytes in the pathogenesis of periodontitis, an adoptive transfer model can be used in immunodeficient mice lacking mature T cells." (PMID 35269683, 2022). "Using single-cell RNA sequencing (scRNA-seq), we investigated the metabolic profile of CD4+ T cells under periodontitis conditions." (PMID 41821617, 2026). "Single-cell RNA sequencing revealed that, under periodontitis conditions, CD4+ T cells exhibited enhanced differentiation toward Th17 cells and increased glycolysis." (PMID 41821617, 2026). "The plasma cells, CD4 memory resting T cells, and follicular helper T cells exhibited the highest relative infiltration proportions in periodontitis samples." (PMID 40267082, 2025). "In this study, treatment of experimental periodontitis with CD73‐enriched RATEVs markedly reduced the activation of the entire periodontal CD4+ T cell compartment." (PMID 40620009, 2025). "CIBERSORT analysis revealed significantly higher infiltration levels of plasma cells, activated CD4+ memory T cells, γδ T cells, and neutrophils in the periodontitis group compared to healthy controls (P < 0.001)." (PMID 40612110, 2025). "Research has shown that naïve T cells differentiate into CD4+ T cells more prominently in periodontitis than in gingivitis." (PMID 40541947, 2025). "T cells are essential for the adaptive immune response, with CD4+ T cells playing a pivotal role in periodontitis pathogenesis." (PMID 40541947, 2025). "Compared to healthy controls, the periodontitis group exhibited significantly higher infiltration of plasma cells, activated CD4+ memory T cells, γδ T cells, and neutrophils, with plasma cells being the most prominent." (PMID 40612110, 2025). "In conclusion, retinoic acid‐induced Treg‐derived EVs suppress CD4+ T cell‐driven inflammation and ameliorate periodontitis, at least in part through CD73/adenosine‐dependent immunomodulatory mechanisms." (PMID 40620009, 2025). "Consistently, the relative abundance of CD4+ T cells (p < 0.05) and specifically Tregs (p < 0.01) compartments were significantly larger in comparison with those present in periodontitis lesions." (PMID 40856197, 2025). "Activated CD4+ memory T cells secrete pro-inflammatory cytokines such as IL-17 and IFN-γ, contributing to tissue destruction and inflammatory bone loss in periodontitis." (PMID 40612110, 2025). "Periodontitis is a highly prevalent inflammatory disease characterised by the accumulation of IL‐17A‐expressing CD4+ T cells in response to dysbiotic oral bacterial biofilms, ultimately leading to RANKL‐mediated alveolar bone resorption and tooth loss." (PMID 40620009, 2025). "In periodontitis samples, compared to healthy ones, the infiltration levels of naive B cells, plasma cells, native CD4+ T cells, activated memory CD4+ T cells, γδT cells, and neutrophils were significantly elevated." (PMID 39045324, 2024).